CASP1 (caspase 1)
Diseases named in the same sentence as CASP1 in open-access papers (continued):
Sharing a sentence is not in itself a finding about the gene and the disease.
infection (continued). "Western blot analysis showed that caspase-1 expression was consistent during infection with both M1T1 GAS isolates." (PMID 33585270, 2020). "The second signal mediated by the bacterial virulence factors e.g. type-1 fimbriae, p-fimbriae and/or α-hemolysin at the site of infection would then promote caspase-1 activation and serine protease release into the cytosol." (PMID 33318544, 2020). "During P. aeruginosa infection, macrophages treated with IFN-γ or IL-17A displayed comparable levels of LDH release and active caspase-1 upon infection with P. aeruginosa, suggesting similar capacities to process pro-IL-1β." (PMID 30455194, 2019). "Caspase-1 activation is an important early innate inflammatory response to infection by viral pathogens." (PMID 31367214, 2019). "Macrophages can promote host defense by sensing and responding to infection via inflammasomes, which are signaling platforms that activate caspase-1 (Eldridge and Shenoy, 2015, Broz and Dixit, 2016)." (PMID 31018119, 2019). "Infection of primed BMDMs with increased MOI of VSV or EMCV led to increased caspase-1 maturation, IL-1β production, and cell death." (PMID 31024004, 2019). "By using western blot we found that NLRP3 was required for CASP1 (p20) and IL-1β (p17) cleavage in response to infection." (PMID 31479495, 2019). "Our findings establish a crosstalk between caspase-4 and caspase-1 during natural infection by virulent EPEC." (PMID 31018119, 2019). "IL-1β is activated by caspase-1, and is critical for the response to infection as it influences the production of NO." (PMID 31775245, 2019). "Caspase-1 activation in MDM mirrored the release of IL-1β, with ~35% of LPS pre-treated cells showing activated caspase-1 after 3 hours exposure to ATP, and ~70% of cells activating caspase-1 in response to a 3 hour infection with live PAO1." (PMID 30978238, 2019). "In this study we sought to identify the redundant pathways that operate downstream of CASP1 for host resistance to infection." (PMID 31251782, 2019). "Taken together, these data demonstrate that LL-37 preferentially accumulates inside airway epithelial cells most compromised by infection with live bacteria, and leads to activation of caspase-1 by a P2X7R and FPRL-1 independent mechanism." (PMID 30978238, 2019). "Inflammasomes are multi-protein complexes that detect infection and other stimuli and activate the Caspase-1 (CASP1) protease." (PMID 31251782, 2019). "For instance, both Nlrc4 and Nlrp3 inflammasomes contribute to caspase-1 activation upon infection with Salmonella Typhimurium." (PMID 31736941, 2019). "Similar to the case in cells infected by the WT strain, infection with the Δplc mutant induced caspase-1 activation and cleavage/release of IL-1β." (PMID 31708887, 2019). "Altogether, these results indicate that infection with virulent strains of HSV-1 promoted Caspase-1 activation in the inflammatory monocytes and neutrophils infiltrating the inflamed corneas." (PMID 31367214, 2019). "The hDPP4-Tg mice infected with MERS-CoV overexpressed caspase-1 in the spleen and showed high IL-1β levels in serum, suggesting that pyroptosis occurred after infection." (PMID 30634407, 2019). "Our results indicated that the levels of active caspase-1 and mature IL-1β induced by either fecal content treatment or infection with E. coli or P. mirabilis were decreased in THP-1 cells pretreated with E. faecalis compared with untreated cells." (PMID 30823406, 2019). "Cleaved caspase-1 was detected in both cell lysates and supernatants at 1 h but was only present in the cell supernatants at 24 h post-infection." (PMID 30964929, 2019). "Similar to the effect on HMGB1 release, an Ad WT infection inhibited the release of mature caspase-1 and IL-1ß subunits into the media." (PMID 31849970, 2019). "IL-1β production was reduced by more than 75% in caspase-1−/− bmDCs (p < 0.01), indicating that it is essential for maturation of IL-1β following infection by both strains." (PMID 31262357, 2019).
infection (continued). "Inflammasomes are cytosolic multi-protein complexes that detect infection or cellular damage and activate the Caspase-1 (CASP1) protease." (PMID 31251782, 2019). "Neither inhibition of FPRL1, nor inhibition of P2X7R, by pre-incubation with WRW4 and KN-62 respectively, were able to inhibit LL-37-mediated activation of caspase-1 during PAO1 infection." (PMID 30978238, 2019). "In contrast, infection with less-virulent HSV-1 clinical isolate KOS63 induce less activation of Caspase-1, IL-1β and IL-18." (PMID 31367214, 2019). "Here we show that although BMDMs infected with S. pneumoniae exhibit large amounts of pro-IL-1β and pro-Caspase-1, accumulation of the processed forms (IL-1β p17 and Casp-1 p20) is highly delayed and remains undetectable until 6 to 12 h post infection." (PMID 31375698, 2019). "Infected cells, in contrast to uninfected cells, readily became Fam-flica positive, indicating that caspase-1 activation was dependent on infection." (PMID 30455194, 2019). "Inflammasome activation by infection with C. perfringens was examined by immunoblot analysis using anti-caspase-1 and anti-IL-1β, as well as by ELISA for IL-1β." (PMID 31708887, 2019). "To further demonstrate the direct involvement of pDCs for early IFN-α and IFN-β production, we depleted pDCs in Aim2−/−, Nlrp3−/−, Casp1−/−, and Il1r1−/− mice by injection of anti-mPDCA-1 antibody at 12 h before and 12 h after infection." (PMID 30470758, 2018). "Treatment of macrophages with FAC prior to infection exerted inhibitory effects towards the expression of Nlrp3 and resulted in less cleavage of both caspase-1 and downstream caspase-7 compared to the solvent." (PMID 29329289, 2018). "Here, we detected higher GFP fluorescence produced by an infection using a baculovirus expressing Sf-caspase-1 shRNA1 from 2 to 4 dpi, but it seemed that the accumulated GFP level was equivalent to the control by 4 dpi." (PMID 29720159, 2018). "Concomitantly, caspase-1 activation results in early pyroptotic damage of host cells—a multifactorial process induced in the first hours of infection, which depends on hyphal formation and certain cell wall components, but not Candidalysin." (PMID 30323213, 2018). "Analysis of the survival of mice infected intranasally with B. thailandensis showed that both Casp1-/- and Casp11-/- mice were significantly less resistant than WT mice and became moribund within 5 days of infection and had to be euthanized." (PMID 29791511, 2018). "C. albicans induces caspase-1-dependent TUNEL staining early during the infection of murine kidneys." (PMID 30065091, 2018). "In order to elucidate the apoptotic pathways in the infected cells following BCG and BCG-MSP1C infections, caspase-1, -3, -8 and 9 activity were measured." (PMID 30112141, 2018). "The adaptor protein apoptosis-associated speck-like protein containing a caspase recruitment domain (ASC) synergizes with caspase-1 to regulate inflammasome activation during pathogen infection." (PMID 30087667, 2018). "We infected BMDMs from C57BL/6, Casp11-/-, Casp1-/-Casp11Tg, Nlrp3-/- and Casp1/11-/- with B. abortus and after 17 hours of infection, we collected supernatant and measured IL-1α release." (PMID 30589883, 2018). "The activation of caspase-1 was reported to stimulate nuclease activity and induce the DNA cleavage in macrophages (J774A.1) after the infection by Salmonella enterica serovar Typhimurium." (PMID 30424790, 2018). "Inflammasomes, which are activated by cell infection and stress, have the potential to trigger the activation of caspase-1, which cleaves the pro-IL-1β and IL-18 into their mature forms, resulting in IL-1β and IL-18 secretion." (PMID 29773990, 2018). "This possibility was also supported in IECs when the first infection was carried out in presence of caspase-1 inhibitor zYVAD." (PMID 30341337, 2018).
infection (continued). "Blockade of pyroptosis in mice by intra-peritoneal administration of Ac-YVAD-CMK (caspase-1 inhibitor) 12 hours prior to infection with S. aureus resulted in reduced pulmonary leakage, LDH release, and bacterial burden in lungs and BALF." (PMID 30248149, 2018). "By contrast, in L. pneumophila-infected THP-1 cells, CASP-1 was only modestly upregulated, with increases ranging from 2- to 3.2-fold between 12 and 48 hours post-infection." (PMID 28873330, 2018). "In the work described here, we examined the role of NLRP3, ASC, and caspase-1/11 in mediating host immune defense against N. caninum in the acute periods of infection." (PMID 30105037, 2018). "Active caspase-1 cleaves pro-IL-lβ and pro-IL-18 into mature IL-lβ and IL-18, which are essential for coordination of immune responses to pathogen infection through allograft neutrophil sequestration, mononuclear phagocyte recruitment, and T-cell activation." (PMID 30087667, 2018). "While we anticipate that caspase-1 mediated activation of pro-IL-1β will contribute to activated IL-1β levels in infection scenarios, we expect that a portion of the IL-1β produced will be the result of increased gene expression." (PMID 30101649, 2018). "Inflammasomes can be triggered by infection or stress, and once activated, caspase-1 is responsible for processing the precursors of IL-1β and IL-18 into their mature forms, which are secreted into the extracellular environment." (PMID 29773990, 2018). "Pyroptosis is a caspase-1-dependent specialized form of cell death that is usually induced in immune cells during infection, especially in macrophages and dendritic cells." (PMID 29616195, 2018). "During in vitro infections, IL-1β secretion was lower in alveolar macrophages from caspase-1/11, NLRP3 or AIM2 KO mice than in WT controls." (PMID 30456207, 2018). "The transcript levels of Sf-caspase-1 in insect cells were determined by semi-quantitative RT-PCR at two days post-infection (dpi) of the recombinant baculoviruses." (PMID 29720159, 2018). "In this study, we found that macrophage infection with LgyLRV1+ parasites resulted in the transcriptional up-regulation of several inflammasome components such as caspase-1, IL-1β, NLRP3, and AIM2." (PMID 29487860, 2018). "The role of caspase-1 in the killing of S. aureus, if Nlrp3−/− mice are protected from infection with this pathogen, is unclear." (PMID 29490278, 2018). "CD11b knockdown increased caspase-1 activation compared to scrambled siRNA control during serum-opsonized Schu S4 infection." (PMID 29632532, 2018). "Infection of mice deficient in NLRP3, ASC, and caspase-1/11 resulted in decreased production of IL-18 and reduced IFN-γ in serum." (PMID 30105037, 2018). "Schu S4 infection leads to minimal caspase-1 activation following ATP addition, whereas Fn infection leads to robust caspase-1 activation." (PMID 29632532, 2018). "The development of lesions was observed, and biopsies of the injection site and various organs, including the kidney, liver, spleen, lung, and testis, were obtained for NLRP3, caspase-1, and interleukin-1β (IL-1β) mRNA analysis during infection." (PMID 29490620, 2018). "The BCG-MSP1C cells also increased the expression of caspase-1 and -9 indicating the involvement of the intrinsic (mitochondrial-mediated) apoptosis pathway during this infection." (PMID 30112141, 2018). "Based on these data, pyroptosis appears to predominate early during infection but caspase-1-independent cell death pathways are also operative after the first 24 h of infection." (PMID 30065091, 2018). "Here, we provide evidence that Casp1/11-dependent pyroptosis occurs in the kidney of infected mice during the early stages of infection." (PMID 30065091, 2018). "We also showed the unique and overlapping functions of caspase-1 and caspase-11 during infection and inflammation." (PMID 28345580, 2017).
infection (continued). "Inflammasome activation-mediated caspase-1 processing and IL-1β cleavage in response to N. caninum infection were observed and were correlated with the time of infection and number of infecting parasites." (PMID 28558839, 2017). "Our data showed increased numbers of naïve CD4+ T cells in the lungs of Nlrp3−/−, Casp1/11−/−, and Asc−/− compared with WT mice at weeks 2, 4, and 10 of infection." (PMID 28740491, 2017). "Consistently, the mortality of Casp1/11−/− mice was also significantly lower compared to WT controls 14 days post infection (d.p.i)." (PMID 28790324, 2017). "The double-stranded DNA sensor AIM2 is known to recruit ASC to trigger puncta formation in response to infection, leading to caspase-1 activation and IL-1β and IL-18 release." (PMID 28771586, 2017). "We have found that P. brasiliensis promoted a NLRP3 inflammasome-dependent caspase-1 activation to release the bioactive IL-1β, and IL-1R1−/− mice displayed a slightly increased survival rate to infection compared with the C57BL/6 mice." (PMID 28871251, 2017). "Studies in mouse models have revealed differential contributions between caspase-1 and caspase-11 in infection and cancer." (PMID 28345580, 2017). "This strain induced IL-1β levels from infected macrophages in a caspase-1-dependent manner similar to wt bacteria, suggesting that SpeB is not involved in caspase-1-independent processing of IL-1β during infection of BMDMs." (PMID 28720729, 2017). "When the inflammasome is assembled in cells of the innate immune system, it induces caspase-1 activation, followed by production of IL-1β or IL-18; IL-1β and IL-18 contribute to host defense during infection." (PMID 28369146, 2017). "Subsequent cleavage of pro-IL-1β and pro-IL-18 into their mature forms is critical for the host response to infection and is accompanied by caspase-1-dependent inflammatory cell death—pyroptosis." (PMID 29085810, 2017). "For example, detection of flagellin results in the rapid induction of caspase-1 dependent pyroptotic cell death, which prevents L. pneumophila replication and infection in mice." (PMID 28261564, 2017). "Addition of DMS (5 μM) to T. cruzi-infected macrophages significantly increased the activation of caspase 1, whereas infection by T. cruzi alone induced a slight increase of caspase 1 activity." (PMID 28733584, 2017). "Activation of caspase-1 inflammasomes induces pyroptosis and contributes to the restriction of infection by flagellated bacteria such as L. pneumophila, Salmonella typhimurium and Burkholderia thailandensis." (PMID 28771586, 2017). "Although there is vivid activity in exploring the role of caspase-1 in B. pseudomallei and other infection models, the in vivo relevance for other caspases have been less well studied so far." (PMID 28686630, 2017). "The inflammasome is an intracellular platform that assembles in response to infection to recruit and activate Caspase-1." (PMID 28650995, 2017). "The activation of IL-1β is regulated by two pathways in response to pathogen infection: transcription of pre-IL-1β mRNA and proteolytical processing of pre-IL-1β protein by caspase-1." (PMID 28060938, 2017). "After three and 6 h of infection IL-1β concentration increased in supernatants reflecting caspase-1 activation." (PMID 28874114, 2017). "Whereas the knowledge about the role of caspase-6 in infectious diseases is very limited, the impact of the pro-inflammatory caspase-1, a component of the inflammasome, has been intensively studied in various infection models." (PMID 28686630, 2017). "An increased influx of total leukocytes characterized as CD45+ cells was detected in the lungs of WT mice compared with Nlrp3−/−, Casp1/11−/−, and Asc−/− mice, which was more expressive in the acute phase (48 h) of infection." (PMID 28740491, 2017). "Rather, after infection with L. monocytogenes, Scid:AtmC/C:Lyz2Cre/+ BMDMs are unable to efficiently convert inactive pro-caspase 1 to active caspase 1 (p20)." (PMID 28362262, 2017).
infection (continued). "Caspase-1 activation enables the processing and secretion of the proinflammatory cytokine interleukin 1β (IL-1β) to control infection." (PMID 28650995, 2017). "Caspases are generally considered to play a role in the induction of cell death in macrophages, as it was shown for the pro-inflammatory caspase-1 after infection with B. pseudomallei." (PMID 28686630, 2017). "In accordance with transcriptional data we observed caspase-1 activation by yeast and hypha infection." (PMID 28874114, 2017). "Although early studies show that mice treated with IFN-α/β are protected from lethality upon intragastric SesT infection, more recent data suggests type I IFNs can benefit or harm the host depending on the functionality of caspase-1." (PMID 28529959, 2017). "In contrast, increased fungal recovery at weeks 2, 4, and 10 of infection were observed in the lungs of Nlrp3−/−, Casp1/11−/−, P2x7r−/−, and Asc−/− mice, that was more prominent at 10 weeks of infection." (PMID 28740491, 2017). "Infections with pdhC::Tn and yvcJ::Tn mutants induced significantly higher levels of caspase-1- and AIM2-dependent cell death in macrophages in comparison to wild-type results as expected." (PMID 28325762, 2017). "X4550(pYA3334-SspH2-EscI) induced higher level of caspase-1 activation than X4550(pYA3334-SspH2) and X4550(pYA3334) after infection." (PMID 28468643, 2017). "Using flagellin-positive bacteria such as L. pneumophila, L. gratiana and L. micdadei, we demonstrated that Asc/Casp1/11-/- mice were highly permissive to bacterial replication and phenocopied infection of Nlrc4-/- mice." (PMID 28771586, 2017). "At 4 weeks of infection, less extensive and severe pulmonary lesions were observed in the lungs of WT in comparison with Nlrp3−/−, Casp1/11−/−, P2x7r−/−, and Asc−/− mice." (PMID 28740491, 2017). "Previous studies have reported that caspase-1 activation clears pathogens such as Salmonella28, Shigella29, and Legionella30, and controls infection." (PMID 27853287, 2016). "We found that caspase-1 activity of J774A.1 cells was increased at 1 h and 3 h after infection with all three S. Typhimurium strains." (PMID 26811498, 2016). "NLRP3 also seeds inflammasome formation, but is activated by a wide array of stimuli and likewise can promote pyroptotic and Asc-dependent, but Caspase-1-independent (pyronecrotic) death of myeloid cells during infection." (PMID 27926940, 2016). "At 8 h and 10 h post-uptake, LDH release following infection by ΔsifA Salmonella was dependent on both caspase-1 and caspase-11." (PMID 27808091, 2016). "The total number of lung cells recovered and the frequencies of T and NK cells were similar between wildtype, Casp1/11-/-, and Nlrp3-/- mice over the course of infection." (PMID 27926940, 2016). "Consistent with this emphasis on apoptosis was the fact that we found caspase-1 and caspase-3 transcription to be up-regulated within the first 72 hours of infection." (PMID 26893019, 2016). "Inflammasomes are cytosolic multi-protein complexes that initiate immune responses to infection by recruiting and activating the Caspase-1 protease." (PMID 27926929, 2016). "NLRP3 is known to cause “pyroptosis”11, a type of caspase-1-dependent programmed necrosis often observed following infection by intracellular pathogens (e.g. Salmonella), or “pyronecrosis”12, a caspase-1-independent cell death." (PMID 27221966, 2016). "Infection with Pg significantly increased expression of genes related to cell death including Bax-1, caspase-1, -3 and -9 and decreased expression of anti-apoptotic Bcl-2 (2-fold)." (PMID 27124409, 2016). "Pyroptosis is part of the host defense against infection and is dependent on the caspase-1 activation." (PMID 27124409, 2016). "Since the cleavage and maturation of IL-1β is mediated by caspase-1 activation, we examined the level of IL-1β 24 h post-infection with the JR32 or the legS2 mutant by ELISA." (PMID 26741365, 2016).